CDKN2A (cyclin dependent kinase inhibitor 2A)
Diseases named in the same sentence as CDKN2A in open-access papers (continued):
Sharing a sentence is not in itself a finding about the gene and the disease.
melanoma (continued). "Furthermore, CDKN2A germline mutations are responsible for the melanoma-astrocytoma syndrome (MIM number 155755), and genetic variants close to both CDKN2A and CDKN2B genes (on the chromosomal locus 9p21) are known to increase the risk for glioma, basal cell carcinoma, and melanoma." (PMID 31968687, 2020). "Currently, CDKN2A, CDK4, and MC1R have been the most investigated genes involved in melanoma pathogenesis." (PMID 33748184, 2020). "Given that our MPRA assay was conducted in melanoma cells, it may be possible that such variants, for example, may only be functioning in the context of oncogenic signaling (e.g., oncogenic BRAF), tumor suppressor loss (e.g., CDKN2A), or immortalizing events (e.g., mutation of the TERT promoter)." (PMID 32483191, 2020). "The scenario of genetic alterations contributing to melanoma gene signature was completed by somatic CNVs, such as gene amplifications in CCND1, CDK4, KIT, MITF, and TERT as well as gene deletions in CDKN2A and PTEN." (PMID 30218391, 2018). "In addition, no CDKN2A families met diagnostic criteria for familial atypical multiple mole melanoma syndrome, and 38.9% (seven of 18) did not report any personal or family history of melanoma." (PMID 31497750, 2018). "In humans, alteration of the genes involved in cell cycle regulation or DNA repair, such as cyclin CDKN2A, p16INK4A and PTEN, is known to be a major element driving the development of melanoma pathogenesis." (PMID 30514258, 2018). "As a confirmation of this, it was recently demonstrated that activation of MEK in BRAFmut cells promotes the development, growth, and maintenance of melanoma in vivo when PTEN and/or CDKN2A losses coexist." (PMID 30218391, 2018). "We chose this cell type because of the importance of the chromosome 9p21 locus including CDKN2A/B and ANRIL in familial and sporadic melanoma, and the availability of a large panel of New Zealand melanoma (NZM)-derived cell lines." (PMID 28653984, 2017). "After the identification of CDKN2A and CDK4 genetic testing of families with hereditary malignant melanoma is possible." (PMID 27804060, 2017). "Genes where a statistically significant difference in mutation rate was observed were APC (p = 9 × 10−7) in CRC, STK11 (p = 0.008) in NSCLC, and CDKN2A (p = 0.02), ERBB4 (p = 9 × 10−4), FLT3 (p = 0.02), and KDR (p = 0.01) in melanoma." (PMID 28196074, 2017). "Thus, we analyzed miRNA expression in 13 individuals with metastatic melanoma, 13 control volunteers, 5 individuals with the p16 mutation (CDKN2A:c.377T>A (p.V126D)) but with no clinical evidence of melanoma incidence, and 8 individuals with the p16 mutation with melanoma." (PMID 26694476, 2015). "Next, we searched for CNAs in genes known to be affected by CNAs in melanoma (BRAF, KIT, MITF, CCND1, CDK4, PTEN, CDKN2A and AKT3)." (PMID 24399611, 2014).
melanoma (continued). "Our in silico significance and proximity analysis of 28 paired cases (13 WGS and 15 targeted cases) identified known (e.g., BRAF, NRAS, CDKN2A, and GRIN2A) and novel (e.g., EPHA3, GRIN2B, and ASXL3) genes involved in melanoma." (PMID 25393105, 2014). "Specifically, FLRT2 was downregulated while MAD1L1, PHLDA2, PLAT, CC2D1B, CDKN2A and RUNX3 were upregulated in both melanoma and in Group 2 and Group 3 SFs." (PMID 23371019, 2013). "Additionally, CDKN2a mutations could only be detected in PCMS or FAMMM-PC families, as none of the CDKN2a mutations were identified in FPC families without melanoma." (PMID 24303367, 2013). "It has been suggested that loss of expression of the gene has prognostic implications for melanoma and codeletion of MTAP with CDKN2A has been investigated in a number of cancers." (PMID 20140953, 2010). "Homozygous deletion (log2 ratio < -1) of the region containing the tumor suppressor gene cyclin-dependent kinase inhibitor 2A (melanoma, p16, inhibits CDK4) (CDKN2A) was observed in two samples, and heterozygous deletion in one sample." (PMID 18522746, 2008). "In another melanoma family with NST (mainly astrocytoma), deletion was found in the CDKN2A/ARF exon 1β." (PMID 15928671, 2005). "A total of 30 individuals among the melanoma-NST families were genotyped using the D9S1748 microsatellite marker, located adjacent to exon 1β of CDKN2A/ARF gene on chromosome 9p21." (PMID 15928671, 2005). "Similarly, chromosome 9 and 10, commonly deleted in these cancers, contain several important suppressor genes such as CDKN2A and PTEN in glioma; XPA, PPP6C, and CDKNA in melanoma; PTCH1 and SUFU in medulloblastoma." (PMID 41537310, 2026). "This suboptimal sensitivity reflects the molecular architecture of the 9p21 locus, where smaller deletions may selectively involve CDKN2A while sparing the adjacent MTAP gene, resulting in melanomas that are p16-negative but retain MTAP expression." (PMID 41596618, 2026). "One patient proved to be carrier of a PV in CDKN2A, even without a personal or family history of melanoma." (PMID 40361347, 2025). "A limitation of this model is that it does not fully represent the biology of all melanoma patients with established brain metastases, as this model is driven by mutant BRAF in the context of Akt1E17K along with Pten and Cdkn2a loss." (PMID 40944916, 2025). "The path to high-CSD melanoma would follow a different trajectory where cells continue proliferating until they face RS, which can be overcome by the acquisition of a TPM and only subsequently lose or down-regulate CDKN2A." (PMID 38371417, 2024). "Particularly, CDKN2A, which codes for the tumor suppressor proteins p16INK4a, p14ARF, and RASSF1A, a regulator of the cell cycle and apoptosis, is often hypermethylated in melanoma." (PMID 39199614, 2024). "This cohort included 27 cancer types, and Skin Cancer (Non − Melanoma) had the highest CDKN2A ALT frequency (46.7% were CDKN2A-DEL and 4.8% were CDKN2A-MUT), followed by melanoma, mesothelioma, pancreatic cancer, head and neck cancer, bladder cancer and gastrointestinal stromal tumor." (PMID 38822443, 2024). "Hence, the adaptation of a five-probe FISH assay targeting against 9p21 (CDKN2A), 11q13 (CCND1), and 8q24 (MYC) has improved the discriminatory power for spitzoid melanomas." (PMID 38247727, 2024). "The most significantly enriched alterations in BRAF-mutant compared with non-BRAF-mutant melanomas were non-duplication SV events in CDKN2A (39/81, 48%; Fisher’s exact, OR = 2.41, 95% CI = 1.24–4.78, P = 7.8 × 10–3)." (PMID 38758740, 2024).
melanoma (continued). "The prevalence of CDKN2A variants increased from 2.1% to 24.6% in SPM and from 10.8% to 44.4% in MPM without and with a positive melanoma family history, respectively." (PMID 39596909, 2024). "Other than MTAP and SEPTIN5, CDKN2A, CDKN2B, HIRA, and DGCR8 were the only recurrently altered cutaneous melanoma genes that were not recurrently altered in acral or mucosal melanomas, which frequently lack the presence of UV-induced mutations." (PMID 38758740, 2024). "Potential treatment alternatives include BRAF/MEK inhibitors, which have been useful in the treatment of various cancers like CDKN2A-negative melanoma, and CDK4/6 inhibitors, which have been approved to treat breast cancer." (PMID 38612819, 2024). "The patient with BRAF (#56) V600+ mutant melanoma who carried both CDKN2A and MITF germline PVs did not respond to adjuvant therapy with TT nor to first-line treatment with ICI." (PMID 36901733, 2023). "Furthermore, 4 melanoma pathway genes (CDKN1A, CDKN2A, CXCR4 and RAD51) were also expressed differently in normal tissues compared with melanoma." (PMID 38070141, 2023). "Furthermore, CDKN1A, CDKN2A, CXCR4 and RAD51 in the melanoma pathway, were also differentially expressed between normal skin and melanoma." (PMID 38070141, 2023). "In BrafV600E-driven murine melanomas lacking Cdkn2a, AKT1 activation was shown to enhance brain metastasis, whereas AKT2 and AKT3 had a less pronounced effect." (PMID 37894325, 2023). "We analyzed 39 cases of atypical Spitz tumor (AST), 10 cases of melanomas with spitzoid features for clinicopathological data and chromosomal alterations, targeting RREB-1 (6p25), CCND1 (11q13), MYB (6q23), together with 9p21 (CDKN2A), using FISH methodology." (PMID 38031947, 2023). "Furthermore, CDKN2A/B co-deletion was seen across multiple cancer types including NSCLC, melanoma, breast, gastrointestinal, and renal cell cancers." (PMID 36915611, 2023). "For example, the progression from a dysplastic nevus to the RGP occurs as a result of unchecked mutations and epigenetic changes in cell cycle and cell survival regulators including PTEN, NF1, CDKN2A, and CCND1 that allow the melanoma cells to bypass senescence." (PMID 36119516, 2022). "For example, one study showed that two years after undergoing genetic testing, CDKN2A carriers without a personal history of melanoma were found to have a 30% increase in adherence to total body skin examination (TBSEs) (p=0.032, one tailed)." (PMID 35372037, 2022). "Despite potential menin involvement in the development of melanoma, germline MEN1 mutations are not prone to this malignancy, as, for instance, has been found with other genes such as CDKN2A." (PMID 36428828, 2022). "These chromosomal regions contain genes [GNAQ (9q21.2), BRAF (7q34), PTEN (10q23.31), CCND1 (11q13.3), RREB1 (6p24.3), MYB (6q23.3), and CDKN2A (9p21.3)] involved in the MAPK pathway, which is consistent with the involvement of this pathway in the pathogenesis of melanoma." (PMID 36614156, 2022).
melanoma (continued). "Interestingly, previous work has suggested that melanomas with low MTAP have decreased cGAS-STING signaling, and MTAP is often co-deleted/silenced with CDKN2A." (PMID 33550279, 2021). "LncRNA antisense noncoding RNA in the INK4 locus (ANRIL), initially identified in a kindred of familial melanoma-neural system tumor with a germ-line deletion of the entire CDKN2A/B locus in 2007, is located at the 9p21 region with 3.9 kb length and also named CDKN2B antisense RNA 1 (CDKN2B-AS)." (PMID 34760707, 2021). "CYT-high primary melanomas on the other hand, did not have recurrent copy number amplifications above the threshold (Q value = 0.25), but rather had loses at 9p21.3 (CDKN2A/B), 9q34.11 (CDK9) and 16q24.2 (IRF8)." (PMID 33779796, 2021). "Previous genome-scale sequencing studies have identified mutations in a number of genes involved in the initiation and progression of melanoma, including BRAF (50%), NRAS (20–30%), neurofibromin 1 (NF1) (10–15%), and cyclin-dependent kinase inhibitor 2A (CDKN2A) (20–40%)." (PMID 34771678, 2021). "Further, FISH to CDKN2A confirmed a hemizygous deletion affecting 9p21.3 in the primary melanoma and diploidy of the same region in metastases (not shown)." (PMID 33664264, 2021). "In our study, we have not detected significant differences between familial melanoma patients regarding CDKN2A status." (PMID 34660619, 2021). "Reduced or absent CDKN2A expression has been observed in melanomas, NSCLC, Hodgkin’s lymphomas, retinoblastomas, and osteosarcomas." (PMID 34361615, 2021). "Unfortunately, a phase 2 study of abemaciclib in 23 melanoma patients with intracranial metastases showed 0% objective responses, but patients were selected irrespective of the presence of the CDKN2A pathway alteration." (PMID 34831002, 2021). "Eight patients, with true features of hereditary melanoma such as MPM and high number of nevi which were negative for germline mutations in CDKN2A, CDK4, and MITF (p.E318K) genes were selected for WES." (PMID 32276436, 2020). "Frequent accompanying mutations in TERTp and CDKN2A were identified, typical for skin primary melanoma, and TMB was not significantly different from primary skin and anus melanoma cases without activating RAF1 fusions." (PMID 32123303, 2020). "The systematic evaluation of over 500 melanoma genomes in the last decade has identified a series of frequently and significantly altered oncogenes and tumor suppressor genes, including BRAF, NRAS, RAC1, NF1, CDKN2A, PTEN, and ARID2." (PMID 33076392, 2020). "Another limitation is that we have not confirmed the gene alterations of the three false-negative melanoma cases with a MYC or CDKN2A probes or a 5 or 7 color FISH probes, since the former probes are unavailable for us." (PMID 32393283, 2020). "In this work, we employed whole exome sequencing (WES) to identify novel susceptibility genes for hereditary melanoma in patients with MPM, who were negative for germline mutations in the genes CDKN2A, CDK4, and MITF (p.E318K)." (PMID 32276436, 2020). "CDKN2A mutations were detected in 6/16 (37.5%) and 3/86 (3.5%) MPM cases with and without family history for melanoma, respectively." (PMID 31382929, 2019). "Alterations identified on the F1H panel included those among CDKN2A (p16/Ink4) and CDKN2B, which are well established in solid malignancies, including lung, breast, pancreatic, melanoma, and a variety of head and neck carcinomas, as well as in pre-B cell acute lymphoblastic leukemia (ALL)." (PMID 29899868, 2018).
melanoma (continued). "Paradoxically, although p14ARF is frequently lost in melanoma through deletion of the CDKN2A locus, it is not possible to stably knock down ARF in melanoma cells expressing this gene (; and data not shown)." (PMID 29137417, 2017). "Conversely, cell cycle genes as CDKN2A and CDK4 have been excluded as predisposing for melanoma in MeLiM." (PMID 29081790, 2017). "Guidelines for melanoma genetic testing have been published as an informal “rule of twos and threes,” but these guidelines apply to CDKN2A testing and are not intended for the more recently described non-CDKN2A melanoma syndromes." (PMID 28283772, 2017). "Targeted deletion of the CDKN2A locus induced the development of various tumors, but not of melanomas." (PMID 29156643, 2017). "We initially focused the analysis to on variants in genes known to cause familial malignant melanoma, but we did not identify any clearly causative variation in these genes (BAP1, CDK4, CDKN2A, MC1R, MITF and PTEN)." (PMID 28623311, 2017). "We observed an inverse correlation between expression of CDKN2A gene transcripts and MCL-1 transcripts in human melanoma clinical samples (INK4a and ARF are not separable in this analysis)." (PMID 27846237, 2016). "Possible co-operators in melanoma development include MET and CDKN2A." (PMID 27439913, 2016). "Our data in this Brazilian cohort of patients are in accordance with previous studies that described absence of CDKN2A epimutation in hereditary melanoma patients." (PMID 26106605, 2015). "Besides the expected coding mutations in BRAF, NRAS, CDKN2A, and other genes detected, significant numbers of recurrent copy number variants and structural rearrangements found in this analysis of 13 WGS cases suggest that they may be important initiating and metastatic events in melanoma." (PMID 25393105, 2014). "No alterations were revealed by sequence analysis in CDKN2A gene except for the rs3814960 and rs11515 variants in the 3′UTR and 5′UTR regions, which are rather common single nucleotide polymorphisms (SNPs) in melanoma patients." (PMID 24884915, 2014). "We therefore sought to determine the incidence of germline PALB2 mutations in a larger series of 201 CDKN2A and CDK4 mutation-negative melanoma families, including 63 with confirmed cases of breast, pancreatic, or multiple other types of cancer." (PMID 24949998, 2014). "Cdkn2a−/−, Tyr-HRAS mice develop spontaneous melanoma before other tumors in the majority of cases." (PMID 27429258, 2013). "Identification of two high-risk MC1R variants in our identical twins in the absence of CDKN2A and CDK4 mutations highlights the contribution of low penetrance genes, such as MC1R, in melanoma susceptibility." (PMID 22978401, 2012). "The CDKN2A protein controls passage through the G1 checkpoint of the cell cycle by inhibiting the phosphorylation of the RB1 protein and of the three tumor suppressors at this locus is the one longest recognized to have a significant role in melanoma." (PMID 20140953, 2010). "Absence of mutations at the CDKN2A or CDK4 loci, even in families with very large numbers of melanoma cases therefore indicate other yet to be identified high penetrance susceptibility genes." (PMID 24281082, 2010).